SEMA4D (semaphorin 4D)
Diseases named in the same sentence as SEMA4D in open-access papers (continued):
Sharing a sentence is not in itself a finding about the gene and the disease.
skin tumors (1 paper, 2021). "Along the same lines, we also highlight activinβA (Inhba) because this member of the TGF-β superfamily was shown to increase malignancy and metastatic spread of skin tumors; semaphorins (Sema6d, Sema4d), which can shape the tumor microenvironment; and ligands of the EGF receptor (Areg, Ereg)." (PMID 33497366, 2021).
tropical spastic paraparesis (1 paper, 2015). "have also demonstrated that Sema4D is overexpressed within the inflammatory demyelinating lesions of HAM/TSP (HTLV-1 associated myelopathy/tropical spastic paraparesis) patients and that Sema4D-overexpressing T cells result in process collapse and destruction of immature OLs but not astrocytes." (PMID 26024919, 2015).
vitiligo (1 paper, 2021). Generalized well circumscribed patches of leukoderma that are generally distributed over symmetric body locations and is due to autoimmune destruction of melanocytes. "Therefore, we obtained the circRNA-ceRNA networks that might have the important roles in vitiligo pathology: hsa_circ_0007716 – hsa-miR-149-5p – ATG13/SEMA4D, hsa_circ_0003770 –hsa-miR-320a-3p – SMAD3 and hsa_circ_0087961 – hsa-miR-27a-3p - PAXILLIN." (PMID 33968138, 2021). "As the results shown that the expression of ANKRD6, ATG13, SEMA4D, SMAD3, and PAXILLIN were all significantly downregulated in vitiligo." (PMID 33968138, 2021). "Furthermore, we detected the expression of target genes such ANKRD6, ATG13, SEMA4D, SMAD3, and PAXILLIN to verify that these circRNA-ceRNA networks are involved in the pathological process of vitiligo." (PMID 33968138, 2021).
tumor (112 papers, 2007 to 2026). "For instance, Sema3A, Sema4C, and Sema4D promote tumor progression by attracting tumor-associated macrophages." (PMID 40103807, 2025). "Tumor-associated macrophages express Sema4D, facilitating neurite development and contributing to tumor innervation." (PMID 40092993, 2025). "Sema4D is a protein that has been shown to be expressed in T lymphocytes, activated B lymphocytes, dendritic cells as well as tumor-associated macrophages, hence providing a more global characterization of OSCC inflammation." (PMID 38903181, 2024). "The expression of SEMA7A and SEMA4D was associated with immunological and metabolic processes occurring within the tumor microenvironment." (PMID 39329961, 2024). "SEMA4D, serving as a pleiotropic signalling protein, is implicated in tumour growth and metastasis, hence why the elevated expression levels of SEMA4D are significantly correlated with patient survival." (PMID 39443302, 2024). "In the process of tumor development, SEMA4D causes T cell exhaustion, leading to a suppressive immune microenvironment with reduced immune cell infiltration, thereby promoting tumor growth." (PMID 37287907, 2023). "In summary, our findings indicate that SEMA4D expression is closely associated with the infiltration of multiple immune cell components in the tumor microenvironment." (PMID 37287907, 2023). "Several semaphorins including Sema3a, Sema3f, Sema3g and Sema6a have been reported to exert tumor growth-inhibiting activities while several others such as Sema4d and Sema6d have been associated with tumor-promoting functions in various cancer types." (PMID 35223842, 2022). "For instance, Sema3A, Sema4C, and Sema4D have been found to promote tumor progression by enrichment of tumor-associated macrophages in TME." (PMID 35155237, 2022). "An elevated expression of Sema4D was closely associated to the presence of lymphatic metastasis, and to poorly differentiated tumors with advanced tumor stage." (PMID 33537086, 2021). "Sema4D/Plexin B1 interaction participated in angiogenesis, regulating tumor-associated macrophages, and control of invasive growth." (PMID 32382577, 2020). "By binding to the plexin B1 receptor on endothelial cells, semaphorin 4D, secreted by the tumor-associated macrophages (TAMs), accelerates tumor angiogenesis and vessel maturation." (PMID 33392191, 2020). "MiR-125b is dysregulated in many human and mouse cancers and in some cell lines, and Sema4D has been reported to be a tumor-associated molecule." (PMID 31394878, 2019). "As for SEMA4D, accumulating evidences illustrated it was a potent inducer of angiogenesis, and its overexpression was associated with tumor progression and poor prognosis in a variety of malignancies." (PMID 31105696, 2019). "We wanted to investigate if the Sema4D+ve/high TAIs observed in the current cohort of HNSCC are of the tumor associated macrophage lineage." (PMID 29541402, 2018). "Sema4D+ve/high tumor cells correlated directly with dense fibrotic peri-tumoral stroma (p=0.0001) and inversely with infiltrate of Sema4D+ve/high tumor-associated inflammatory cells (TAIs) (p=0.01)." (PMID 29541402, 2018). "PSR stained bright red the dense peri-tumoral stroma associated with the Sema4D+ve/highHNSCC tumor cells." (PMID 29541402, 2018). "Sema4D+ve/high TAIs proved to be statistically negatively associated with Sema4D expression in tumor cells (p= 0.011), where Sema4D-ve/low expression in tumor cells correlated with increased infiltration of Sema4D+ve/high TAIs in the peri-tumoral stroma." (PMID 29541402, 2018). "Recently, we found that HNSCC-associated Sema4D modulates an immune-suppressive, tumor-permissible environment by inducing the expansion of myeloid derived suppressor cells." (PMID 29541402, 2018).
tumor (continued). "The mechanistic roles of Sema4D and Plexin-B1 in the tumor microenviroment such as tumor angiogenesis, regulation of tumor-associated macrophages as well as the invasiveness of the tumor itself are highlighted in the following discussion." (PMID 20858260, 2010). "In this study, we explored the expression and immune cell infiltration patterns of SEMA4D using multiple bioinformatics datasets and analyzed the relationship between SEMA4D expression with immune checkpoints, tumor mutational load (TMB), microsatellite instability (MSI) and immune function." (PMID 37287907, 2023). "Our results also suggest that decreased SEMA4D expression after tumor progression to advanced stages may be associated with decreased immune cell infiltration." (PMID 37287907, 2023). "However, several investigations reported that tumor-associated macrophages (TAMs) considerably induced expression of SEMA4D in colon cells, and this overexpression is remarkably associated with lymphatic metastasis and specific histological types." (PMID 34337054, 2021). "In addition, Sema4D can induce neurite outgrowth, and this semaphorin is mainly expressed in tumor-associated macrophages promoting tumor angiogenesis, but possibly also tumor innervation." (PMID 32555170, 2020). "Therefore, we selected Sema4D, which is closely associated with tumor development, to uncover the miRNA–mRNA network and function of ALV-J in tumorigenesis." (PMID 31394878, 2019). "This might indicate a positive feedback mechanism, by tumor associated macrophages expressing Sema4D and might explain the two subtypes of Sema4D+ve/high tumor cells versus Sema4D+ve/high TAIs." (PMID 29541402, 2018). "The association of Sema4D with malignancy is a matter of relative increase in the level of expression, where our cut off value for the examined tissue was diffuse strong expression (75%-100%), by the tumor cells or TAIs." (PMID 29541402, 2018). "Whether Sema4D expression by tumor cells correlates with mutational burden in stage III malignancy versus stage IV, is still to be investigated." (PMID 29541402, 2018). "A statistically insignificant positive association between Sema4D expression in primary tumor cells and nodal metastasis was observed, specifically patients with nodal metastasis had higher levels of Sema4D staining in the primary tumor (p= 0.12)." (PMID 29541402, 2018). "For instance, semaphorin 3A and semaphorin 4D have been extensively documented to promote tumor progression, immune suppression, and nerve–tumor interactions, contributing directly to PNI progression." (PMID 41009819, 2025). "Semaphorin4D (SEMA4D) is a protein that plays a significant role in the tumor microenvironment of epithelial ovarian cancer (EOC)." (PMID 40330466, 2025). "The risk model incorporated immune-related genes such as GBP2, SEMA4D, and KIR2DL4, which demonstrated distinct tumor expression profiles and strong prognostic value." (PMID 40319421, 2025). "In the context of EOC, SEMA4D influences the differentiation of monocytes into M2 macrophages, which are known for their pro-tumor activity." (PMID 40330466, 2025). "Our group has previously proposed a scoring system, to assess the pattern of tumor histological inflammatory subtype (HIS) using the expression of Semaphorin 4D (Sema4D)." (PMID 38903181, 2024). "We subsequently investigated the potential associations between the expression levels of SEMA7A, SEMA4D, ADAM8, and ADAMTS10 proteins and the characteristics of tumor size (T), lymph node involvement (N), metastasis (M), and disease stage." (PMID 39329961, 2024). "Our results showed that SEMA4D knockdown delays tumor growth and resulted in a significant decrease in PD1, LAG3, and TIM3 expression in TME, and a trend of decreased TIGIT expression." (PMID 37287907, 2023).
tumor (continued). "The results of RT–qPCR showed that the level of SEMA4D mRNA in tumor tissues was significantly higher than that in adjacent tissues (p=0.0269), and IHC staining proved that SEMA4D protein was also highly expressed in tumors (p<0.0001)." (PMID 37287907, 2023). "In conclusion, we explored SEMA4D expression patterns with bioinformatics methods and determined its relationship with immune cell infiltration and with CD8+Tex cells, providing a new perspective for exploring the role of SEMA4D in tumor immunity." (PMID 37287907, 2023). "Further studies are needed to elucidate the precise role of SEMA4D in tumor progression in these specific cancer types." (PMID 37287907, 2023). "In conlusion, this study provides a more comprehensive perspective of SEMA4D regulation of tumor immunity, which provide a new option for cancer immunotherapy." (PMID 37287907, 2023). "Normal and tumor tissues were stained with the same antibody for IHC, and differential expression of SEMA4D was analyzed to ensure accurate results." (PMID 37287907, 2023). "In our experiments, SEMA4D expressed on tumor cells plays an important role in inducing an inhibitory immune effects." (PMID 37287907, 2023). "We further analyzed the expression levels of SEMA4D in early and advanced stages of various tumors to investigate its potential role in tumor progression." (PMID 37287907, 2023). "Sema4D and its receptor, Plexin-B1, play crucial roles in the process of immune regulation, angiogenesis, and tumor progression." (PMID 37096066, 2023). "As a ligand of Plexin-B1, Sema4D plays important roles in tumor cell proliferation, survival, and migration." (PMID 37096066, 2023). "Tumor cells secrete SEMA4D, which stimulates myeloid-derived suppressor cell (MDSC) differentiation, enhances the immunosuppressive function of MDSCs, and inhibits T cell proliferation and IFN-γ production." (PMID 37287907, 2023). "In vivo experiment, we transplanted B16-F10R cells in the mice and observed the size and weight of tumors treated with nivolumab, tumor volume and weight were significantly delayed in Sema4D-shRNA group mice as compared to Sema4D-NC group mice." (PMID 37096066, 2023). "Recent studies have highlighted the mechanisms behind SEMA4D signaling and its angiogenic effect in tumor models." (PMID 37504226, 2023). "SEMA4D regulates the invasion and migration of tumor cells and participates in tumor angiogenesis through various mechanisms." (PMID 37287907, 2023). "Tumor cells and immune cells have complex interactions in the immune microenvironment, and SEMA4D expressed on tumor cells participates in editing the inhibitory immune microenvironment." (PMID 37287907, 2023). "The results of our study suggest a potential role of SEMA4D in immune function during tumor development." (PMID 37287907, 2023). "Sema4D, from the immune semaphorin family, is related to angiogenesis and tumor progression and is vital in immune regulation." (PMID 36777724, 2023). "Compared with the control group, we observed that tumor growth was significantly slower in the SEMA4D knockdown group." (PMID 37287907, 2023). "Numerous studies have been investigating the role of SEMA4D in promoting cancer angiogenesis and the role of SEMA4D/Plexin B1 signaling in enhancing tumor vascularization." (PMID 37504226, 2023). "PlexinB1 is a high-affinity SEMA4D receptor that can activate downstream signaling in tumor cells after binding to SEMA4D, influencing their biological activity." (PMID 35794581, 2022). "The production of SEMA4D by TAMs in the tumor stroma has been shown to sustain tumor angiogenesis and vessel maturation; while SEMA4D expressed by cancer cells sustains angiogenesis by binding plexin-B1 expressed by endothelial cells." (PMID 35440004, 2022).
tumor (continued). "Whereas the majority of described osteoclast-derived molecules act by enhancing bone formation, Semaphorin 4D (SEMA4D) is one of the few known to suppress bone formation, and it is the only one that has also been implicated in tumour progression." (PMID 36138226, 2022). "In HNSCC, tumor cell-derived Sema4D inducing MDSC polarization corresponded with an inhibition in T-cell activation and an increase in arginase-1, TGF-β, and IL-10 production." (PMID 35155237, 2022). "The combination of SEMA4D and PlexinB1 can also activate the c-Met tyrosine kinase, leading to tumor growth." (PMID 35794581, 2022). "Recent reports showed a significant correlation between the HIS-IE tumor tissue and higher levels of the soluble immune biomarker Semaphorin 4D (HsS4D) in plasma, compared to HIS-INF." (PMID 36338570, 2022). "HIS-IE was previously associated with higher levels of soluble Semaphorin 4D (HsS4D) in plasma, and higher transcriptional levels of osteopontin (OPN) in the tumor tissue, compared to HIS-INF." (PMID 36338570, 2022). "Antibody neutralization of Sema4D disrupts this gradient of expression, enhances recruitment of activated monocytes and lymphocytes into the tumor, and shifts the balance of cells and cytokines toward a proinflammatory and antitumor milieu within the TME." (PMID 35155237, 2022). "Sema4D/CD100 have critical roles in the immune system, nervous development, tumor progression, angiogenesis and skeletal muscle development." (PMID 36010604, 2022). "Soluble Sema4D is released by proteolytic cleavage of the transmembrane form of Sema4D and circulates in the blood, which interacts with the tumor microenvironment." (PMID 35401878, 2022). "SEMA4D plays key roles in various mechanisms involved in cancer including tumor angiogenesis, cancer progression, metastasis, and also, tumor microenvironment regulation." (PMID 34337054, 2021). "We further defined a tumor-promoting effect of SEMA4D recovery on cell viability, colony formation, migration and invasion of KYSE30 and KYSE450 cells." (PMID 33957921, 2021). "We examined the Sema4D positive IC infiltrate in the invasive tumor front, peritumoral stroma, and tumor core." (PMID 33776991, 2021). "Scoring of the histological inflammatory subtype (HIS) was carried out using Sema4D immunohistochemistry on the tumor tissue." (PMID 33776991, 2021). "In the present study, after the SEMA4D knockdown, the percentage of viable tumor cells decreased, and the rate of apoptosis increased." (PMID 34337054, 2021). "The goal of the present study was to determine the changes of tumor progression following the inhibition of SEMA4D expression using siRNA." (PMID 34337054, 2021). "In breast cancer mouse model, TAMs were demonstrated as a main source of SEMA4D that promoted ECs migration, vessel organization and tumor growth in vitro." (PMID 34209679, 2021). "The interactions of Semaphorin 4D (Sema4D) with its receptor Plexin-B1 regulate angiogenesis and tumor invasive growth." (PMID 34403220, 2021). "Sema4D also promotes tumor migration and invasion through Rho activation, microtubule organization, and epithelial mesenchymal transition." (PMID 33776991, 2021). "The 10 cases were selected to include replicates of the HIS patterns (INF versus IE &/or ID), and Sema4D +ve and −ve tumor cells." (PMID 33776991, 2021). "For example, a gain in semaphorin 4D was shown to support tumor cell transmigration through the blood–brain barrier and MYC has been suggested as a key factor for the adaptation of disseminated tumor cells to the activated brain microenvironment." (PMID 35008251, 2021). "In the tumor cells (TC), Sema4D showed membranous and/or cytoplasmic staining that ranged from negative/weak to moderate/strong staining." (PMID 33776991, 2021). "In fact, Sema4D/PlexinB1 signaling has been reported to promote tumor angiogenesis and invasive growth in experimental models 34,35." (PMID 33537086, 2021).